TNF (tumor necrosis factor)
Diseases named in the same sentence as TNF in open-access papers (continued):
Sharing a sentence is not in itself a finding about the gene and the disease.
Cerebral ischemia (continued). "In contrast to our results regarding pro-inflammatory cytokines in the circulation, we found that cerebral ischemia significantly up-regulated the expression of IL-1β, TNF-α, and IL-6 mRNA in cortical tissue." (PMID 38102677, 2023). "Irisin also contributes to the neuroprotective effects of physical exercise against cerebral ischemia by mitigating the release of the pro-inflammatory cytokine tumor necrosis factor (TNF)-α via the Akt and ERK1/2 signaling pathways." (PMID 37047523, 2023). "Our results demonstrated that the expression of TNF-α, IL-6, and NF-κB p65 increased after reperfusion, while the expression of IκB-α and IL-10 decreased, suggesting that cerebral ischemia triggers inflammatory response." (PMID 36970418, 2023). "Microglial cells, the resident macrophages of the brain, are activated within minutes after the onset of cerebral ischemia and release proinflammatory agents such as tumor necrosis factor alpha (TNF-α) or interleukin-1 beta (IL-1β)." (PMID 37958527, 2023). "In this context, previous studies showed that deletion of TNFα reduces remyelination repair process in multiple sclerosis and cerebral ischemia mouse models, indicating a protective role for TNFα." (PMID 36937050, 2023). "Studies have shown that the expression levels of TNF-α, IL-1β, and other inflammation-related factors peak after 3 days of ischemic encephalopathy." (PMID 36855153, 2023). "A previous study has shown that NLXTD reduces tumor necrosis factor alpha (TNF-α) protein expression in the frontoparietal cortex of reperfused rats with cerebral ischemia." (PMID 35668929, 2022). "After cerebral ischemia/reperfusion, microglia release interleukin (IL)-1β, IL-6, and tumor necrosis factor-α (TNF-α)." (PMID 35602556, 2022). "The ELISA results showed that the levels of IL-1β, IL-6, and TNF-α were abnormally increased in the serum of rats with cerebral ischemia." (PMID 35467483, 2022). "Endothelial Panx1 can regulate TNF-α-induced leukocyte adhesion and emigration in venules, as well as modulate pulmonary and cerebral ischemia/reperfusion injury." (PMID 35315432, 2022). "Taken together, these findings suggested that TNF-α neutralization has clinical therapeutic significance, so it is necessary to develop TNF-α antibody which can treat the prognosis of cerebral ischemia." (PMID 35781632, 2022). "CPB triggers cerebral ischemia and hypoxia and inflammation, increasing release of inflammatory factors such as IL-1β, IL-6, TNF-α." (PMID 35526011, 2022). "EA can scavenge free radicals generated during cerebral ischemia, increase the activity of antioxidant enzymes, and inhibit the expression of inflammatory factors such as IL-1β and TNF-α by activating the MAPK and Nf-κB pathways to reduce cell death." (PMID 36142849, 2022). "Many previous studies, including ours, have confirmed that DOR activation can inhibit the release of TNF-α in cerebral ischemia–reperfusion injury and markedly attenuate the inflammatory response." (PMID 36457949, 2022). "The damaged brain cells produce a large number of platelet activating factors, TNF, IL-6, and other inflammatory mediators after cerebral ischemia." (PMID 35950034, 2022). "It has been reported that in the acute phase after the induction of cerebral ischemia, activated microglia are the predominant source of TNFα." (PMID 36004858, 2022). "After the SD rats were modeled by MCAO and orally administered YYTNG, the levels of TNF-α and IL-18 in the plasma of the rats with cerebral ischemia-reperfusion at different time points revealed a downward trend." (PMID 36016577, 2022). "In the early stage of inflammation, white blood cells can be activated to release toxic oxygen metabolites, among which TNF-α and IL-1β are closely related to cerebral ischemia injury." (PMID 35664672, 2022). "The results showed that cerebral ischemia/reperfusion injury can promote platelet spreading, and TNF-α neutralization can reverse this process." (PMID 35781632, 2022).
Cerebral ischemia (continued). "In rats, it can also inhibit neuronal apoptosis and intimal hyperplasia following cerebral ischemia, as well as the inflammatory response induced by the TNF-α/NF-κB pathway." (PMID 36589679, 2022). "Rhodiola sp. can reduce TNF-α, transforming growth factor beta 1, and IL-6 levels in the BALF in a concentration-dependent manner and inhibit inflammatory injury caused by cerebral ischemia in rats, slowing the progression of brain edema." (PMID 35432571, 2022). "TNF-α and IL-1β are classical inflammatory cytokines after cerebral ischemia, while IL-4 and IL-10 are anti-inflammatory cytokines." (PMID 35496902, 2022). "The most important cytokines related to inflammation in cerebral ischemia include IL-1β, TNF-α, IL-6, IL-10, and transforming growth factor-β (TGF-β)." (PMID 35656190, 2022). "The expression levels of the pro-inflammatory cytokines tumor necrosis factor alpha (TNF-α), interleukin (IL)-6, IL-8, IL-1β, and cyclooxygenase-2 were increased after cerebral ischemia." (PMID 36420646, 2022). "The M1 type microglia excretes a large number of inflammatory factors such as IL-6, IL-1β, IL-12 and TNF-α, which aggravate cerebral ischemia/reperfusion injury." (PMID 35658867, 2022). "Nurr1 is a member of the orphan nuclear receptor 4 family, and its high expression can significantly inhibit the expression of TNF-α in microglia and reduce neuronal inflammatory and cytotoxic responses induced by cerebral ischemia-reperfusion." (PMID 36275741, 2022). "After brain ischemia, levels of the pro-inflammatory IL-1β and TNF-α were elevated in the MCAo + vehicle group (155% and 187% of sham control levels, respectively), whereas anti-inflammatory IL-10 levels were not significantly changed (88% of sham values)." (PMID 35631536, 2022). "Brain ischemia significantly upregulated mRNA expression of TNF‐α, IL‐1β, and IL‐6, which were inhibited by BMPER." (PMID 34904361, 2022). "It has been accepted that berberine can decrease inflammatory agents-induced IL-1B and TNF-a ensuing inflammation in cerebral ischemia." (PMID 34600570, 2021). "In the study of cerebral ischemia-reperfusion injury, the expression of TNF-α, IL-1β, and IL-6 was significantly decreased after Acacetin treatment compared with the middle cerebral artery occlusion group." (PMID 34594156, 2021). "Microglia are rapidly activated during cerebral ischemia and become key cells in the inflammatory reaction in the brain, secreting pro-inflammatory cytokines such as IL-6, IL-1β and TNF-α, which are involved in microglia-mediated neurological injury." (PMID 34504432, 2021). "In an animal model of cerebral ischemia, a dramatic up-regulation of TNF protein and mRNA has been shown." (PMID 34877406, 2021). "Blocking endogenous TNFα via monoclonal anti-TNFα antibodies in rats has been shown to decrease cerebral ischemia." (PMID 33585095, 2021). "TNF-α generated through monocytes and macrophages and its over generated due to activation of inflammation related cells during the cerebral ischemia, that boost the local inflammation reaction in the brain tissue." (PMID 34795593, 2021). "After cerebral ischemia-reperfusion, inflammatory cell activation is followed by the release of proinflammatory factors such as TNF-α and IL-1β." (PMID 34853620, 2021). "For instance, TNF-α antagonism through soluble TNF receptor (sTNFR) or monoclonal antibodies directed against TNF-α provide neuroprotective effects after cerebral ischemia." (PMID 34572077, 2021). "At the molecular level, the tight junction ZO-1 protein is a downstream target of TNF-α signaling through proteolytic mechanisms, and its level drops in cerebral ischemia." (PMID 34073455, 2021). "All kinds of borneol significantly reduce TNF-α levels, while D-borneol and DL-borneol reduce IL-1β levels and DL-borneol reduces IL-6 in cerebral ischemia/reperfusion models." (PMID 34017247, 2021).
Cerebral ischemia (continued). "For example, α-pinene was able to attenuate neuro-inflammation in a rat model of focal cerebral ischemia-reperfusion by decreasing both the gene and protein expression of TNF-α and IL-1β." (PMID 35145398, 2021). "Consistently with previous reports, our present study provided additional evidence of anti-inflammatory and neuroprotective effects of TNF-α inhibition in cerebral ischemia injury." (PMID 34073455, 2021). "Etanercept, an inhibitor of TNF-α, shows neuroprotection after experimental cerebral ischemia and also improves clinical outcomes in the context of chronic stroke." (PMID 34572077, 2021). "Catalpol can effectively relieve cerebral ischemia-reperfusion injury, reduce inflammatory reaction, and reduce the contents of IL-1 β, IL-6, and TNF-α." (PMID 33505489, 2021). "Inflammation is the main pathogenesis for cerebral ischemia, and a marked inflammatory reaction is evoked by cerebral I/R with increased pro-inflammatory factors, such as TNFα, IL-1β, and IL-6." (PMID 34591125, 2021). "Under brain ischemia, activated microglia initiate phagocytosis and the production of reactive oxygen species and inflammatory mediators, including interleukin (IL)-1β, tumor necrosis factor (TNF)-α, and interleukin (IL)-6." (PMID 33530496, 2021). "Proinflammatory pathways that are activated due to brain ischemia-reperfusion are characterized by TNF-α and interleukin-1β (IL-1β) synthesis." (PMID 33953854, 2021). "Systemic application of the TLR9 ligand cytosine-guanine oligodeoxynucleotides (CpG-OdN) before MCAO-induced brain ischemia significantly decreased ischemic damage through a TNF-dependent process and PI3K/Akt signaling pathway." (PMID 34200356, 2021). "Similar to other studies, preconditioning with LPS before induction of brain ischemia protects the neuronal tissues against the cytotoxic effects of the TNF-α pathway in mice." (PMID 34200356, 2021). "The brain-related pathways demonstrated that PKall, KNG, B2KR, IL-6, TNF-α, IL-1β, LGALS-3, and PAR 2 were linked to superoxide anion generation and brain ischemia." (PMID 34867349, 2021). "It was recently described that DiOHF increases apoptosis, and reduces the production of tumor necrosis factor (TNF)-α, as well as the DNA damage in rats with brain ischemia–reperfusion." (PMID 34358066, 2021). "Elevated COX-2 and TNF-α protein levels were detected in ipsilateral cortical tissues after cerebral ischemia." (PMID 32492962, 2020). "The levels of TNF-α in the ischemic cortex of the rats reached the highest level one day after pMCAO and decreased 3 d after cerebral ischemia." (PMID 32922507, 2020). "In another report, pre-treatment with fenofibrate, pioglitazone, and their combination in rats with cerebral ischemia improves inflammatory and apoptotic markers, such as TNF-α." (PMID 32707656, 2020). "Electroacupuncture can effectively decrease the expression of NF-κB p65, IL-1β, and TNF-α after cerebral ischemia and inhibit the conversion of microglia to the M1 phenotype after ischemic brain injury." (PMID 32922507, 2020). "A previous study reported that IL-6 has a favorable prognostic effect on cerebral ischemia and dermatological diseases because it inhibits the production of tumor necrosis factor-α and IL-1, which are classical proinflammatory cytokines." (PMID 33379208, 2020). "The levels of TNF-α and IL-1β in the electroacupuncture group were lower than those in the model group 2 h and 1 d after cerebral ischemia (P < 0.05)." (PMID 32922507, 2020). "Cerebral ischemia results in activation of NF-κB in microglia which release inflammatory factors, such as TNF-α, ICAM-1, IL-6." (PMID 32153408, 2020). "Another study demonstrated its neuroprotective effect in cerebral ischemia/reperfusion injury by irisin-induced reduction in the activation of apoptosis and TNFα and IL-1β expression in brain tissue." (PMID 33096842, 2020).
Cerebral ischemia (continued). "It seems that KLF4 does not directly influence the expression of TNF-α but acts to inhibit TNF-α-induced activation of NF-κB to alleviate the cerebral ischemia-induced cerebral vascular inflammation." (PMID 32264912, 2020). "At the early stage of cerebral ischemia, the activation of glial cells and infiltration of leukocytes in the injured tissue produced great amounts of pro-inflammatory factors such as TNF-α and IL-1β, contributing to BBB damage and hemorrhagic transformation." (PMID 32508671, 2020). "After cerebral ischemia, the expression of microglial markers (Iba-1 and CD11b) increased, and NF-κB p65, IL-1β, and TNF-α expression gradually increased." (PMID 32922507, 2020). "During cerebral ischemia, activated microglial cells migrate to inflammatory sites and produce excessive neurotoxic and inflammatory mediators, such as TNF-α, IL-1β, IL-6, MCP-1, MIP-1, PGE2 and NO, which exacerbate neuronal damage." (PMID 33373319, 2020). "A previous study showed that the levels of TNF-α, IL-6, infarct volume, and cerebral edema increased in rats subjected to cerebral ischemia-reperfusion." (PMID 32153408, 2020). "Three days after cerebral ischemia, electroacupuncture obviously decreased the levels of IL-1β (P < 0.01); however, it had little effect on TNF-α expression (P > 0.05)." (PMID 32922507, 2020). "When microglial cells were activated after cerebral ischemia, the levels of NF-κB p65 and the expression of IL-1β and TNF-α, which are mediated by NF-κB p65, gradually increased, and the dynamic changes were generally temporally consistent." (PMID 32922507, 2020). "A preceding study has indicated that the pro-inflammatory cytokines TNF-α and IL-1β were significantly downregulated in brain ischemia and microglia by the overexpression of Hsp70." (PMID 32899721, 2020). "Dexmedetomidine pretreatment attenuated neurological injury, brain lesions and expression of inflammatory factors (IL-1β, IL-6, TNF-α) after brain ischemia (P < 0.05)." (PMID 33287729, 2020). "The increase of IL-1β enhances TNF-α level in a synergistic way and these inflammatory cytokines promote the neuroinflammation process and brain ischemia damage." (PMID 32963745, 2020). "That study also demonstrated that tacrolimus attenuates the expression of cytokines, such as TNF-α, in glia after cerebral ischemia." (PMID 31087207, 2019). "In line with a Cox-2/PGE2 model of BBB permeability, inhibition of Cox-2 during neuroinflammation induced by traumatic brain injury, cerebral ischemia, and TNF-α has previously been found to attenuate BBB disruption in vivo." (PMID 31779628, 2019). "QKL treatment decreased TNFα significantly (Vs MCAO, p = 0.0001), after TNF-α had been upregulated by the cerebral ischemia-reperfusion injury." (PMID 31747940, 2019). "Cerebral ischemia-induced up-regulation of inflammatory cytokines such as TNFα and IL-1β are known to stimulate the expression of MMPs that can digest tight junction and basement membrane proteins, and thus contribute to BBB disruption." (PMID 31261992, 2019). "TNF-α also enhances the permeability of the blood-brain barriers thereby contributing to secondary brain injury following cerebral ischemia." (PMID 31231488, 2019). "The neuroprotective role of OX-A has been suggested to be due to the effect on microglia activation; in different models of cerebral ischemia the neuropeptide is able to prevent the increment of LPS-induced tumor necrosis factor alpha (TNF-α)." (PMID 31024456, 2019). "In adult rats, remifentanil preconditioning has been shown to reduce brain damage from cerebral ischemia reperfusion and to decrease TNF-α expression, ROS production, and caspase-3 and -9 activities." (PMID 31068895, 2019). "Tumor necrosis factor-α (TNFα) plays a major role in inflammatory and vascular processes after cerebral ischemia." (PMID 31032149, 2019).
Cerebral ischemia (continued). "Toll-like receptors (TLRs) play key roles in cerebral ischemia and reperfusion injury by inducing the production of inflammatory mediators, such as interleukins (ILs) and tumor necrosis factor-alpha (TNF-α)." (PMID 29867706, 2018). "Toll-like receptor 4 (TLR4) plays a key role in cerebral ischemia and reperfusion injury by inducing the production of inflammatory mediators, such as interleukins (ILs) and tumor necrosis factor-alpha (TNF-α)." (PMID 29867706, 2018). "The most important cytokines that are related to inflammation in cerebral ischemia are IL-1, TNF-α, IL-6, IL-10, and transforming growth factor-β (TGF-β)." (PMID 29540536, 2018). "In accordance with this data, cannabidiol has exerted its anti-inflammatory effect through TNF-α inhibition in cerebral ischemia." (PMID 28539998, 2017). "Our results showed that cerebral ischemia induced upregulation of IL-6, TNF-α, and IL-1β significantly, when compared with that of the control group." (PMID 28855861, 2017). "TNF-α has been initially considered as a proinflammatory cytokine, but interestingly, in the case of cerebral ischemia, it was found that this cytokine has a neuroprotective effect and is involved in the brain tissue repair (Wang, Yang, & Yu, 2001)." (PMID 28446953, 2017). "Following cerebral ischemia, the expression of inflammatory cytokines such as interleukin-1 beta (IL-1β), tumor necrosis factor-alpha (TNF-α), and IL-6 are elevated." (PMID 28645333, 2017). "NF-κB is involved in the inflammatory responses that potentiate cerebral ischemic damage, thus activating many genes involved in the pathogenesis of cerebral ischemia, such as iNOS, IL-1β, TNF-α, ICAM-1, COX-2, and IL-6." (PMID 29220411, 2017). "Here, these pro-inflammatory cytokines (IL-1β, IL-6, and TNF-α) were chosen as markers to evaluate the inhibition of the inflammatory response at 24 h after cerebral ischemia and reperfusion in the hippocampus." (PMID 28769792, 2017). "The involvement and upregulation of TNF-α and TNFR in many pathological manifestations including cerebral ischemia have been implicated (Botchkina, Meistrell, Botchkina, & Tracey, 1997)." (PMID 28539998, 2017). "Our previous study suggested that HS can suppress the release of inflammatory mediators TNF-α and IL-1β in activated microglia and reduce the infarct size and brain water content following cerebral ischemia." (PMID 28288585, 2017). "Brain ischemia triggers inflammatory responses and produces cytotoxic substances including TNF, IL-1β, iNOS, and other proinflammatory mediators, resulting in more neuronal damage." (PMID 29234386, 2017). "In vascular cognitive impairment (VCI) and other disorders resulting from cerebral ischemia, TNFα (expressed by vascular and perivascular cells) can promote pro-inflammatory and pro-coagulant effects on the endothelia." (PMID 27144978, 2016). "Cerebral ischemia induces the expression of TNF-α, IL-1β, IL-6 and inducible nitric oxide synthase (iNOS), which leads to the upregulation of endothelin receptors in the cerebral arteries." (PMID 27115869, 2016). "The anti-inflammatory properties of FBD can be further attributed to IL-1β, TNF-α, and IL-8 downregulation during the acute phase of cerebral ischemia." (PMID 27703487, 2016). "We tested spatial reference memory in the TNFα-Tg rat to determine if chronic elevation of TNFα affects cognitive performance before and after focal cerebral ischemia." (PMID 27144978, 2016). "The effect of myeloid TNF ablation in cerebral ischemia was assessed by comparing infarct volumes in TNFfl/fl to LysMcreTNFfl/fl mice after pMCAO." (PMID 27384243, 2016). "Microglia are activated following cerebral ischemia and increase their production of the neuro- and immunomodulatory cytokine tumor necrosis factor (TNF)." (PMID 27384243, 2016).